PON1 (paraoxonase 1)
Diseases named in the same sentence as PON1 in open-access papers (continued):
Sharing a sentence is not in itself a finding about the gene and the disease.
atherosclerosis (continued). "Modulating PON1 expression might be a treatment objective with significant results in limiting the prevalence of atherosclerosis." (PMID 38474211, 2024). "It is thus inconceivable that PON1 has evolved to combat atherosclerosis." (PMID 36873390, 2023). "The increase in PON-1 in hypothyroid dogs of our study differs from the decreases described in humans with hypothyroidism; in which low PON-1 values are considered a risk of atherosclerosis associated with this disease." (PMID 36732758, 2023). "PON1 is known to mediate an enzymatic protection of LDL against oxidative modification and has been strongly implicated with the potential treatment of metabolic diseases including atherosclerosis and obesity." (PMID 37189434, 2023). "This could explain the increase of PON-1 found in dogs with hypothyroidism in our study, and this increase in PON-1 could also be one of the reasons why dogs have lower risks of atherosclerosis than humans." (PMID 36732758, 2023). "Not surprisingly, decreased PON-1 activity has been associated with the development of several diseases such as atherosclerosis, psoriasis, Sjögren's syndrome, and rheumatoid arthritis." (PMID 36344783, 2023). "The critical epidemiological test of whether PON1 activity was relevant to future atherosclerosis, however, came with reports of prospective studies." (PMID 36873390, 2023). "Overexpression of the PON1/2/3 cluster facilitated collagen synthesis, narrowed the necrotic core area, and decreased oxLDL and inflammatory markers, inhibiting mitochondrial dysfunction and stimulating plaque stability to alleviate atherosclerosis." (PMID 35386842, 2022). "PON1 polymorphism modifies the effect of carotenoids on different diseases related to oxidative stress, not necessarily related to atherosclerosis." (PMID 35889799, 2022). "In addition, paraoxonase 1 (PON1) is an HDL-associated protein that binds to HDL-C and is mechanistically linked to atherosclerosis." (PMID 36014836, 2022). "PON1 has been shown to prevent the development of atherosclerosis." (PMID 35889799, 2022). "In addition to inhibiting early plaque formation, PON1 was found to lower oxidative stress and improve vasomotor function during established atherosclerosis." (PMID 35889799, 2022). "Altered PON-1 activities in different HDL subclasses could be essential factors in the development of atherosclerosis in patients with CKD as well as end-stage kidney disease." (PMID 36140402, 2022). "PON1 is thought to prevent atherosclerosis, mainly due to its anti-oxidant activity." (PMID 36118876, 2022). "PON-1 may be a determinant of resistance to the development of atherosclerosis, perhaps by hydrolyzing phospholipid and cholesteryl-ester hydroperoxides." (PMID 36140402, 2022). "PON1 activity has been reported in atherosclerosis and cardiovascular disease." (PMID 35711939, 2022). "It has been demonstrated that PON1 could have beneficial effects in numerous diseases such as atherosclerosis, CVD, diabetes mellitus, and neurodegenerative diseases by modulating relevant signalling pathways involved in inflammation and oxidative stress." (PMID 35883764, 2022). "In another study including persons with diabetes, persons with coronary heart disease but no diabetes, and control subjects, high CRP levels were related to low PON1 activity, suggesting that there is a mechanistic link between inflammation and the development of atherosclerosis." (PMID 34332593, 2021). "PON1 has been shown to help HDL protect against the development of atherosclerosis by preventing the accumulation of lipoperoxides in LDL, inactivate oxidized lipids, enhance cholesterol efflux from macrophages, and stimulate HDL-mediated eNOS-dependent NO production." (PMID 34639003, 2021). "Knockout of the Pon1 gene exacerbates atherosclerosis in mice." (PMID 34418970, 2021).
atherosclerosis (continued). "Our results show that pomegranate peel and aril extracts increase serum PON1 activity, which may delay the development and progression of atherosclerosis." (PMID 34574329, 2021). "Moreover, increased PON1 activity improves prognosis in patients with severe overt symptoms of atherosclerosis." (PMID 33670025, 2021). "We also demonstrated that an abnormally low concentration of the antiatherosclerotic protein paraoxonase/arylesterase 1 (PON1) in HDL associates with both albuminuria and atherosclerosis as measured by coronary artery calcification in patients with type 1 diabetes." (PMID 34634315, 2021). "Ablating PON1 in atherosclerosis-prone mice enhances development of atherosclerosis." (PMID 34331945, 2021). "PON1 is known to have effects on preventing cardiovascular diseases and atherosclerosis." (PMID 33033457, 2020). "Administration of SQ seems to have several positive effects on cardiovascular system, reducing atherosclerosis through induction of paraoxonase 1 (PON1) protective against the development of atherosclerosis, enhancing peripheral blood flow and improving central arterial elasticity." (PMID 32748847, 2020). "PON1 knockout mice are more sensitive to atherosclerosis and Hcy thiolactone-induced neurotoxicity." (PMID 32967340, 2020). "PON1 is an HDL-associated protein which inhibits lipid peroxidation and has been associated with lower atherosclerotic risk in population studies and reduced atherosclerosis in animal models." (PMID 33033318, 2020). "PON1 enzymes have anti-inflammatory and antioxidant properties and may protect against atherosclerosis." (PMID 32280543, 2020). "As previously discussed, PON-1, PSH, and MDA are linked to surrogate measures of cardiovascular disease in the general population; however, their association with markers of atherosclerosis, e.g., peripheral ED, in RA is unknown." (PMID 32854225, 2020). "PON-1 is frequently observed to be reduced in inflammatory conditions and chronic disease, and genetic-knockout mice lacking PON-1 have been shown to have both impaired antioxidant effects and increased risk of atherosclerosis." (PMID 30675710, 2019). "On the contrary, low PON1 activity seems to result in a decreased functional efficiency of HDL, which in turn increases the risk of developing inflammatory diseases, including (but not limited to) atherosclerosis." (PMID 31390816, 2019). "It has been demonstrated that glycated PON1 also results in endothelial dysfunction in T2DM through endoplasmic reticulum stress, which is widely associated with other pathologies, such as atherosclerosis, obesity, NAFLD, neurodegenerative disorders, and cancer." (PMID 31430977, 2019). "Therefore, the decreased concentration of PON1 plays an important role in pathogenesis of atherosclerosis." (PMID 31737129, 2019). "It allowed the hypothesis that PON1 is responsible for the protection of LDLs against oxidation, which is important in the pathogenesis of atherosclerosis." (PMID 31737129, 2019). "For example, hemodialysis partially restores PON1 arylesterase and lactonase activity, which may afford protection against oxidative stress and the progression of atherosclerosis in patients with end stage renal disease." (PMID 31234489, 2019). "Thus, many studies have been conducted to link a high-glucose-level state with HDL, PON1, and atherosclerosis." (PMID 30151068, 2018). "The beneficial effects of PON1 on the inhibition of atherosclerosis might be more pronounced in FH patients because they are more prone to develop atherosclerosis than the general population." (PMID 30044465, 2018). "PON1 shows a protective effect through the detoxification of neurotoxic agents, such as acute organophosphate insecticides and somansarine, and especially against lipid peroxidation, which is very important in atherosclerosis and diabetes pathogenesis." (PMID 29995097, 2018). "PON1 activity is lower in patients with atherosclerosis and in inflammatory diseases." (PMID 28376720, 2017).
atherosclerosis (continued). "Thus future studies should pay more attention to mechanism of effect of PON1 on atheroma formation and establishment of novel therapeutic approaches for atherosclerosis prevention/treatment via manipulating PON1 availability and activity." (PMID 29118945, 2017). "Once these issues have been resolved, these compounds could be included as nutraceuticals and functional foods capable of increasing PON1 activity, thereby helping with the long-term prevention of atherosclerosis and other chronic ailments." (PMID 28212288, 2017). "Whether the TG-rich and CE-poor HDL particles contain different content of PON1 or the change of PON1 activity, by which contribute to atherosclerosis." (PMID 29212549, 2017). "Beside, future pharmacological studies about atherosclerosis could focus on producing medications with ability of inducing PON1 activity or expression." (PMID 29118945, 2017). "PON-1 associates with HDL to prevent its oxidation by copper ions as well as reducing the peroxide and aldehyde content of HDL, this interaction also lessens LDL atherogenic potential, thus potentially reducing the risk of development of atherosclerosis." (PMID 28596970, 2017). "Furthermore, myeloperoxidase (MPO) and paraoxonase 1 (PON1) are HDL-associated proteins that bind to HDL and are mechanistically linked to inflammation, oxidative stress, and atherosclerosis." (PMID 28611100, 2017). "The role of ApoA-I and PON1 in inhibition of atherosclerosis has been reported." (PMID 27642496, 2016). "PON1 gene is associated with several human diseases, related to oxidative stress including cardiovascular disease, Parkinson’s disease and cancer and is inversely associated to the risk of CVD, particularly to atherosclerosis." (PMID 27338244, 2016). "Some case-controlled studies have shown that the PON1 R allele is very common in CHD patients, indicating that the PON1192 polymorphism may be a risk factor for atherosclerosis." (PMID 26241956, 2015). "Human paraoxonase 1 (PON1) is an esterase that catalyzes the hydrolysis of organophosphate paraoxon and that hydrolyzes oxidized lipids, which are involved in the initiation and progression of atherosclerosis." (PMID 26241956, 2015). "Paraoxonase 1 (PON1) protects against atherosclerosis by preventing the oxidation of blood lipids." (PMID 26114387, 2015). "Parenteral administration of partially purified PON1 can ameliorate experimental atherosclerosis." (PMID 26528181, 2015). "The anti-inflammatory and antioxidant effects of HDL may be promoted by decreasing serum MPO activity and increasing PON1 activity, thus deterring the development of atherosclerosis." (PMID 25604880, 2015). "Others indicated that PON1 enzyme activity, versus phenotype alone, may be a more meaningful marker of atherosclerosis and coronary heart disease." (PMID 24682159, 2014). "This activity elevation may be useful in reduced PON1 activity in diabetes, atherosclerosis and other cardiovascular diseases." (PMID 24644436, 2014). "The reduction of PON1 and free radical scavenging activity with age could have a considerable impact on the increased incidence of atherosclerosis with age." (PMID 24971380, 2014). "Recently, Paraoxonase −1 (PON1) which accounts for most of the antioxidant effect of high density lipoprotein (HDL) cholesterol has been presented as a potential therapeutic agent against atherosclerosis development." (PMID 25551104, 2014). "Also, recombinant PON1 protein has a protective effect against apoptosis and ROS production in macrophages, suggesting that further study is needed to understand how PON1 functions on atherosclerosis." (PMID 24465855, 2014). "Their findings suggested that low level of PON1 activity in adult patients with NS may be related to atherosclerosis due to oxidant-antioxidant imbalance." (PMID 24693505, 2013).
atherosclerosis (continued). "Serum paraoxonase (PON1), an HDL-associated enzyme, plays an important role in the protection of LDL from oxidation, and it may attenuate the development of atherosclerosis." (PMID 22536511, 2012). "Such roles suggest that PON1 has crucial effects on the initial steps of atherosclerosis." (PMID 22824324, 2012). "Although PON1 enzyme activity is a more important factor in atherosclerosis and coronary heart disease than PON1 genotype, it is interesting to observe that there was a higher frequency of the RR isoform of the 192 polymorphism in healthy subjects than in those with chronic HCV infection." (PMID 22824324, 2012). "As atherosclerosis and oxidative stress are known to be involved in the pathogenesis of ischemic colitis, in the present study, we investigated the possible changes in PON-1 activity in an experimental model of ischemic colitis, for the first time in the world literature." (PMID 23197980, 2012). "Moreover, mice with combined PON1/apoE KO exhibited more atherosclerosis than apoE KO mice and their LDL particles were more susceptible to oxidation." (PMID 22824324, 2012). "The ability of PON1 to protect against both organophosphate toxicity and atherosclerosis is also supported by experimental studies, since PON1-knockout mice were more sensitive to the toxic effects of chlorpyrifos, and developed atherosclerosis when fed a high-fat diet." (PMID 22615820, 2012). "As expected, MIP-2 alpha a cytokine rather not related to atherosclerosis is not affected by the PON1 polymorphism." (PMID 21569287, 2011). "Since the amount of MIP-2 alpha, a cytokine rather not related to atherosclerosis, is not affected by PON1 polymorphism, the observed changes of TNF-alpha and MCP-1 levels observed in the current study are most likely specific." (PMID 21569287, 2011). "Hence, enhanced PON1 antioxidant capacity was found to be associated with reduced TNF-alpha levels, probably protective against atherosclerosis." (PMID 21569287, 2011). "An overexpression of human PON1 in mouse models of atherosclerosis decreased aortic lesion size." (PMID 20604930, 2010). "Further studies with larger populations are needed to explore whether there is a strong relationship between PON1 activity and atherosclerosis in H. pylori infection." (PMID 20804546, 2010). "Paraoxonase-1 (PON1), an enzyme associated with high-density lipoprotein particles, participates both in the hydrolysis of oxidized lipids (thus protecting against atherosclerosis) and in the hydrolysis of organophosphates." (PMID 19672401, 2009). "These authors also found that there was significantly more PON1 present in LPDS from subjects with Type 2 diabetes than healthy control subjects and that this may be one reason for the accelerated atherosclerosis associated with Type 2 diabetes." (PMID 18937674, 2008). "Animal studies have strongly supportedthe protective role of PON1 in atherosclerosis." (PMID 16882531, 2006). "Additionally, mice knocked out for PON1 develop atherosclerosis, suggesting that PON1 may also serve as an atheroprotective." (PMID 40457011, 2025). "Thus, PON1 is also considered as a clinical parameter reflecting the HDL multiple functions, and many studies have investigated associations of PON1 with a wide range of diseases, including atherosclerosis, cancer, and other infectious diseases." (PMID 41049124, 2025). "Besides that, PON1 is correlated with the severity of atherosclerosis." (PMID 38474211, 2024). "Furthermore, there is good evidence that PON-1 protects lipids against peroxidation by preventing low-density lipoprotein oxidation, a critical factor involved in the pathogenesis of inflammatory diseases such as atherosclerosis, diabetes and cancer." (PMID 35313365, 2023). "However, in support of an important role for PON1, genetic deficiency of neither apoA1 nor LCAT in humans is, unlike PON1 deficiency, conspicuously associated with premature atherosclerosis." (PMID 36873390, 2023).
atherosclerosis (continued). "However, while the mechanistic role of PON1 in the detoxication of specific organophosphates is clear-cut and well understood, its protective role against atherosclerosis is not fully understood, in part due to the undefined nature of its putative pro-atherogenic targets." (PMID 37175471, 2023). "Furthermore, PON1 could reduce the secretion of monocyte Chemoattractant Protein-1 (MCP-1) by arterial endothelium in atherosclerosis." (PMID 35883764, 2022). "Thus, enhancement of PON1 activity could be a useful approach to attenuating atherosclerosis development." (PMID 36290781, 2022). "Additionally, IL-6 might upregulate the expression of an anti-atherosclerosis molecule PON1 gene at a transcriptional level through the AKT/IKK/NF-κB activation pathway in human hepatocyte-derived HepG2 cells." (PMID 35453382, 2022). "Interestingly, PON1 is also thought to be related to atherosclerosis and lipid peroxidation." (PMID 33628379, 2021). "Our study shows multifaceted associations of PON1 with dyslipidaemia, ICS, and cardiovascular mortality in HD patients providing arguments for the consideration of PON1 as a therapeutic target in the prevention of atherosclerosis and its complications in uremic patients." (PMID 33762698, 2021). "However, the correlation of subclinical atherosclerosis with PON1 activity has been reported." (PMID 32214403, 2020). "In addition, it has been shown that inhibition of LDL oxidation prevents the upregulation of MCP1 secretion, providing evidence that PON1 may be able to inhibit atherosclerosis at an early stage." (PMID 32708891, 2020). "In addition, NK‐01 could increase the content of paraoxonase 1, which could prevent atherosclerosis." (PMID 31660132, 2019). "Given the proposed important role of PON1 in atherosclerosis, it is reasonable to hypothesize that its hepatic production and release in the blood circulation should be finely regulated by endogenous factors, in particular by those playing a role in disease pathogenesis." (PMID 31390816, 2019). "The progression of atherosclerosis was inhibited in LDL receptor-deficient mice supplemented with quercetin (an antioxidant), which is found in pomegranates, and increased hepatic expression of the PON1 gene as well as the associated activity of the enzyme in serum." (PMID 30360466, 2018). "Since the association of PON1 with high-density lipoprotein (HDL) stabilizes the enzyme, these beneficial effects of pomegranate consumption on serum PON1 stability and activity could lead to retardation of atherosclerosis." (PMID 28212288, 2017). "Similarly, PON1 knockout mice are more susceptible to atherosclerosis and their HDL is less able to prevent the accumulation of lipid peroxides on human LDL, whereas transgenic rodent models expressing human PON1 are protected against atherosclerosis." (PMID 26528181, 2015). "Thus the reduction of PON1 and free radical scavenging activity with age could have a considerable impact on the increased incidence of atherosclerosis with age." (PMID 24971380, 2014). "In addition, several articles support the hypothesis that lower PON1 activity is correlated with an increase in oxidative stress, leading to the development of atherosclerosis." (PMID 25405733, 2014). "One of those antioxidant enzymes is paraoxonase (PON1) which is associated with high-density lipoprotein (HDL); PON1 was shown to protect lipoproteins, HDL, and low-density lipoprotein (LDL), from oxidation which has been accepted to play a pivotal role in the development of atherosclerosis." (PMID 25431786, 2014). "Vice versa, overexpression of human PON1 resulted in a reduced atherosclerotic lesion formation in mice, further suggesting that reduced paraoxonase activity may contribute to the development of atherosclerosis." (PMID 24222847, 2013). "Though PON-1 polymorphism is linked to Atherosclerosis, it could not explain its relationship with steroid-induced ONFH." (PMID 24206655, 2013).